VPS26C (VPS26 endosomal protein sorting factor C)
Description:
Component of the commander complex that is essential for endosomal recycling of transmembrane cargos; the commander complex is composed of the CCC subcomplex and the retriever subcomplex. Component of the retriever complex, which is a heterotrimeric complex related to retromer cargo-selective complex (CSC) and essential for retromer-independent retrieval and recycling of numerous cargos such as integrin alpha-5/beta-1 (ITGA5:ITGB1). The recruitment of the retriever complex to the endosomal membrane involves CCC and WASH complexes. In the endosomes, drives the retriever and recycling of NxxY-motif-containing cargo proteins by coupling to SNX17, a cargo essential for the homeostatic maintenance of numerous cell surface proteins associated with processes that include cell migration, cell adhesion, nutrient supply and cell signaling. (Microbial infection) The heterotrimeric retriever complex, in collaboration with the CCC complex, mediates the exit of human papillomavirus to the cell surface.
Synonyms: DCRA; DSCR3; DSCRA
Tractability: PROTAC: ubiquitination databases record sites on it.
Gene: Protein-coding gene on chromosome 21 (37,223,417 to 37,267,919, reverse strand). Ensembl gene ENSG00000157538.
Subcellular location: Endosome
Subcellular location (Human Protein Atlas): Mitochondria
Gene Ontology:
Molecular function: protein binding
Biological process: endocytic recycling; intracellular protein transport
Cellular component: nucleus; protein-containing complex; endoplasmic reticulum membrane; endosome membrane; endosome
Genetic constraint (gnomAD): Loss-of-function variants: 18 observed, 31.44 expected, observed/expected ratio (o/e) 0.57, 90% interval 0.4 to 0.85. The upper end of that interval is the gene's LOEUF score, 0.85, which puts it in group 3 of 6, group 1 being the genes least tolerant of losing a copy. Missense variants: 317 observed, 400.34 expected, observed/expected ratio (o/e) 0.79, 90% interval 0.72 to 0.87. Synonymous variants: 132 observed, 158.17 expected, observed/expected ratio (o/e) 0.83, 90% interval 0.72 to 0.96.
Homologues: Orthologues: chimpanzee VPS26C (99% identical), macaque VPS26C (99% identical), dog VPS26C (95% identical), guinea pig VPS26C (94% identical), rabbit VPS26C (92% identical), mouse Vps26c (92% identical), tropical clawed frog vps26c (86% identical), rat Vps26c (85% identical), zebrafish vps26c (78% identical), pig VPS26C (72% identical), chimpanzee VPS26C (58% identical), Drosophila melanogaster CG4074 (52% identical). Paralogues in human: VPS26A (23% identical), VPS26B (22% identical).
Diseases named in the same sentence as VPS26C in open-access papers:
VPS26C is named in the same sentence as 6 diseases in open-access papers, as found by Europe PMC text mining. Sharing a sentence is not in itself a finding about the gene and the disease. The quoted sentences say what the papers report.
influenza (1 paper, 2024). An acute viral infection of the respiratory tract, occurring in isolated cases, in epidemics, or in pandemics; it is caused by serologically different strains of viruses (influenzaviruses) designated A, B, and C, has a 3-day incubation period, and usually lasts for 3 to 10 days. "We co-expressed the retriever complex-specific protein VPS26C, tagged with a double human influenza hemagglutinin (HA) tag, alongside the shared protein between retromer and retriever complexes, VPS29, tagged with a V5 tag." (PMID 38884339, 2024).
microphthalmia (1 paper, 2023). Congenital or developmental anomaly in which the eyeballs are abnormally small. "A similar search of DR17 using the term microphthalmia resulted in 22 genes significant for the small eyes phenotype: Aldh1a3, Aff4, Bmp4, Cdk4, Cox6b1, Cxcr4, Dync1li1, Eef1d, Fgd1, Gne, Grh12, Mab21l2, Maf, Med13l, Mllt10, Mthfd2, Pex6, Phgdh, Ssr1, Stim1, Tdo2, and Vps26c." (PMID 36737727, 2023).
VPS26C also shares sentences with these, for which no sentence is quoted: Down syndrome (3 papers); glioblastoma (2); cancer (1); preeclampsia (1).